RAD51 (RAD51 recombinase)
Diseases named in the same sentence as RAD51 in open-access papers (continued):
Sharing a sentence is not in itself a finding about the gene and the disease.
ovarian carcinoma (continued). "Above all, these results suggested to us that miR-509-3 mediated Olaparib sensitization by directly impairing HMGA2-ATM axis as well as downregulating RAD51 in ovarian cancer." (PMID 32005272, 2020). "The ATR inhibitor overcomes fork stabilization in BRCA-deficient cells by preventing RAD51 loading onto stalled forks and triggering MRE11-mediated fork degradation, as shown in PARP-resistant ovarian cancer cells and PDXs." (PMID 32029455, 2020). "Patients with pathogenic mutations in these RAD51 regulator genes, particularly RAD51C and RAD51D, have a higher risk of developing ovarian cancer [RAD51C, OR 8.3 (95% CI 5.43–12.48); RAD51D, OR 3.17 (95% CI 1.31–7.42)]." (PMID 33015624, 2020). "In contrast, in high-grade serous BRCA-wildtype ovarian cancer cells, prexasertib synergised with olaparib by inhibiting G2/M arrest, as well as also inhibiting olaparib-induced RAD51 foci formation." (PMID 32260355, 2020). "A phase I clinical trial revealed synergistic effects between olaparib and the PI3K inhibitor alpelisib in epithelial ovarian cancer, which are most likely based on HR suppression through reduced RAD51 protein levels and RAD51 foci formation." (PMID 32029455, 2020). "A recent study reported that BET proteins regulated RAD51 in ovarian cancer cells, and we showed that knockdown of each BET family member (BRD2, BRD3, and BRD4) in DMS273 cells led to downregulation of Rad51 expression." (PMID 33134168, 2020). "The presented study demonstrated a significant association of studied 135G/C and Q356R polymorphisms of RAD51 and BRCA1 genes, respectively, with the occurrence of ovarian cancer." (PMID 30712190, 2019). "Deficiency in the canonical RAD51 paralogs, such as RAD51C and RAD51D, are linked to familial breast and ovarian cancer predisposition." (PMID 31665741, 2019). "Recent studies using the ability to form RAD51 foci in ovarian cancer organoids confirms that this assay is predictive of response to PARPi." (PMID 30871186, 2019). "The RAD51 foci formation test has been shown to predict the response to PARP inhibitors in ovarian cancer." (PMID 30669514, 2019). "Of the 12 upregulated genes VEGFA, HJURP, CCNE2, and RAD51 were also upregulated in the tissue of ovarian cancer patients according to in silico microarray data (Oncomine)." (PMID 31319587, 2019). "A number of the RAD51 mediators have now been added to the more comprehensive breast and ovarian cancer screening panels (i.e., PALB2, RAD51C, RAD51D, XRCC2)." (PMID 30551670, 2018). "Mutations in the human RAD51 paralogs (RAD51B, RAD51C, RAD51D, XRCC2, XRCC3, and SWSAP1) are found in a subset of breast and ovarian cancers." (PMID 30551670, 2018). "To investigate the possible prognostic values of let-7e, BRCA1 and Rad51 in ovarian cancer, we first analyzed their correlation with the clinicopathological characteristics of EOC patients." (PMID 28376831, 2017). "pS1946P is located in exon 11 where the BRC motif binds to RAD51 and belongs to the ovarian cancer cluster region (OCCR)." (PMID 27907908, 2016). "Since Rad51 depletion enhances type I IFN signalling in vitro, we examined patients with breast or ovarian cancer due to RAD51C mutation for signs of autoimmunity." (PMID 27230542, 2016). "After overexpressing miR-506 in a panel of ovarian cancer cell lines, we analyzed the down-regulated genes via a microarray and observed a decrease in RAD51 levels." (PMID 26369335, 2015). "Quantification of RAD51 nuclear focus formation has been used to assess HR competence in epithelial ovarian cancer ascites primary cultures, and was correlated with response to PARPi in vitro." (PMID 26198537, 2015). "Pubmed, Cochrane library and Chinese Biomedical Literature Database (CBM) were searched for case-control studies on RAD51 135G/C polymorphism and the risk of SCCHN, colorectal cancer, ovarian cancer and acute leukaemia published up to Oct 31, 2013." (PMID 24457040, 2014).
ovarian carcinoma (continued). "We evaluated the functional impact of 17-AAG on HR in HR proficient ovarian cancer cell lines using the RAD51 foci formation after ionizing radiation (IR) assay." (PMID 24798692, 2014). "We performed a meta-analysis including 6836 cases and 8507 controls from 22 case-control studies to evaluate the association between RAD51 135G/C polymorphism and risk of SCCHN, colorectal cancer, ovarian cancer and acute leukaemia." (PMID 24457040, 2014). "The present study analysed the five RAD51 paralogs (RAD51B, RAD51C, RAD51D, XRCC2, XRCC3) to estimate their contribution to breast and ovarian cancer predisposition." (PMID 24139550, 2013). "The association with RAD51 paralogs and the frequent copy number loss of HELQ in ovarian cancers suggests HELQ as a candidate ovarian cancer predisposition gene." (PMID 24005565, 2013). "Mutation analyses in further genes of RAD51 paralogs have uncovered RAD51C and RAD51D as susceptibility genes in hereditary breast and ovarian cancer families." (PMID 24025454, 2013). "Moreover, ABL1-mediated Y739 phosphorylation of SYCP2 promotes function of SYCP2 at sites of R-loops by facilitating RAD51 localization and repair, contributing to ovarian cancer cell survival." (PMID 40918650, 2025). "In conclusion, this study demonstrates that RAD51 protein expression offers a valuable tool for predicting chemotherapy sensitivity, platinum resistance recurrence, and survival outcomes in patients with advanced epithelial ovarian cancer." (PMID 41199843, 2025). "RAD51 protein expression offers a valuable tool for predicting chemotherapy sensitivity, platinum resistance recurrence, and survival outcomes in patients with advanced epithelial ovarian cancer." (PMID 41199843, 2025). "NEAT1 knockdown sensitized ovarian cancer cells to Olaparib by targeting RAD51-HR." (PMID 38356722, 2024). "However, the research in RAD51 foci assessment for ovarian cancer has been rapidly evolving, partly triggered by the need to make the assay more accurate and practical for clinical use." (PMID 38725623, 2024). "RAD51 IHC, which is convenient, cost-effective, and can be easily assessed with a light microscope used for routine pathological practices, has the potential to be incorporated in the management of ovarian cancer." (PMID 38725623, 2024). "The expressions of NEAT1 and RAD51 in ovarian cancer cells were negatively correlated." (PMID 38356722, 2024). "Therefore, Rad51 serves as a determinant of platinum resistance and a novel therapeutic target to overcome immune escape in Rad51-high epithelial ovarian cancer." (PMID 35875146, 2022). "Carriers of a mutation in any of the RAD51 genes were more likely than noncarriers to have a family history of ovarian cancer, although this difference was not statistically significant." (PMID 36544182, 2022). "The most notable example is the independent validation of treatment-induced nuclear Rad51 foci as a functional marker of homologous recombination (HR) within clinical samples of breast and ovarian cancer and its ability to predict patient response to PARP inhibitors and platinum drugs." (PMID 34680224, 2021). "Whether in the general patients, or in patients receiving platinum-based chemotherapy, or in taxol-treated patients, high RAD51 expression deteriorated survival prognosis of ovarian cancer." (PMID 33952262, 2021). "In the present study, we profiled the role of RAD51 in ovarian cancer." (PMID 33952262, 2021). "Subsequently, we examined the effect of RAD51 on drug responsiveness of ovarian cancer cell lines." (PMID 33952262, 2021). "Deep deletion was the most common genetic alteration of RAD51 observed in ovarian cancer." (PMID 33952262, 2021). "Therefore, RAD51 is a feasible biomarker for predicting drug responsiveness and survival in ovarian cancer." (PMID 33952262, 2021). "Here, we explored the predictive value of RAD51 in ovarian cancer." (PMID 33952262, 2021).
ovarian carcinoma (continued). "In summary, RAD51 is a pivotal gene in ovarian cancer and confers ovarian cancer dependency." (PMID 33952262, 2021). "After searching UALCAN, we obtained 557 genes correlated with RAD51 in TCGA ovarian cancer." (PMID 33952262, 2021). "Thus, the authors suggest that the mechanisms that drive RAD51 expression in ovarian cancer are independent from a recombination defect." (PMID 33779077, 2021). "As a significantly overexpressed fitness gene, RAD51 conferred ovarian cancer dependency." (PMID 33952262, 2021). "We established optimal parameters with regard to RAD51 foci cut-off (≥2) and HRD threshold (15%) using matched endometrial and ovarian carcinoma specimens for which HR status had been established using a RAD51-based test that required ex vivo irradiation of fresh tissue (RECAP test)." (PMID 34203855, 2021). "Notably, in patients with ovarian cancer, a significant number of PVs were identified in the moderate penetrance RAD51 genes; RAD51C (1.5%) and RAD51D (1%), followed by the MMR and ATM genes." (PMID 34326862, 2021). "The role of RAD51 in other ovarian cancer subtypes needs further exploration." (PMID 33952262, 2021). "Ovarian cancer tissues expressed more RAD51 than normal ovary tissues." (PMID 33952262, 2021). "Ovarian cancer had pronounced RAD51 expression and RAD51 conferred ovarian cancer dependency." (PMID 33952262, 2021). "Here, we investigated whether germline loss-of-function variants affecting another RAD51 paralog gene, RAD51B, are also associated with breast and ovarian cancer." (PMID 34635660, 2021). "Ovarian cancer has pronounced RAD51 expression compared with normal ovary." (PMID 33952262, 2021). "In ovarian cancer, RAD51 expression was significantly elevated." (PMID 33952262, 2021). "In summary, RAD51 has broad connections with ovarian cancer." (PMID 33952262, 2021). "Ovarian cancer tissues had pronounced RAD51 expression compared with paired normal tissues." (PMID 33952262, 2021). "Therefore, high RAD51 expression indicates platinum resistance and unfavorable survival in ovarian cancer patients." (PMID 33952262, 2021). "RAD51 has predictive value in ovarian cancer and can be exploited as a predictive biomarker." (PMID 33952262, 2021). "Rad52 loads Rad51 onto replication protein A (RPA)-coated ssDNA in yeasts, while in mammals Rad51 loading is facilitated by BRCA2, whose mutations predispose humans to breast and ovarian cancer." (PMID 32355220, 2020). "Population studies have showed that deleterious mutations in RAD51 paralogs RAD51C and RAD51D confer susceptibility to epithelial ovarian cancer, while specific polymorphisms of the RAD51 gene could be used as a biomarker for increased risk of OC." (PMID 32512900, 2020). "Loss-of-function variants in RAD51C and RAD51D increase the risk of breast and ovarian cancer, but the same has not been demonstrated for other RAD51 paralogs, or for RAD51 itself that plays a major role in HR repair." (PMID 33333735, 2020). "A significant correlation was revealed between single nucleotide polymorphisms of DNA double-strand break repair genes via homologous recombination (HR) XRCC3-Thr241Met (rs861539), XRCC2--41657C/T (rs718282), BRCA1-Q356R (rs1799950) and RAD51–135 G/C (rs1801320) and ovarian cancer development." (PMID 30712190, 2019). "We first confirmed that, as in other types of cancer cells, berberine was able to induce oxidative DNA damage and to downregulate RAD51 in ovarian cancer cells, two conditions that would render the cancer cells more reliant on PARP for survival and proliferation." (PMID 28981112, 2017). "Also, in BRCA1-deficient ovarian cancer cells, RAD51 paralogs XRCC2 and XRCC3 are capable of loading enough RAD51 onto stalled forks (in an ATR-dependent manner), thus providing proto-resistance to PARPi that can evolve to full resistance." (PMID 29355244, 2017).
ovarian carcinoma (continued). "Rare pathogenic mutations in RAD51 paralogs RAD51C and RAD51D have been identified in breast and ovarian cancer families and confer a high risk specifically for ovarian cancer whereas a homozygous missense mutation in RAD51C (FANCO) was found in a Fanconi anemia patient." (PMID 27149063, 2016). "As PI3K inhibitor BKM120 as single-agent led to an increase in γH2AX with a paralleled decrease in the abundance of homologous recombination protein RAD51 in ovarian cancer cells, we next determined if additional use of PARP inhibitor Olaparib would further dampen cellular response to DNA damage." (PMID 26909613, 2016). "Similarly, PI3K inhibitor GDC-0941 as single-agent also led to an increase in γH2AX and a decrease in the abundance of RAD51 in ovarian cancer cell lines examined." (PMID 26909613, 2016). "Further functional study demonstrated that miR-506 could augment the response to cisplatin and olaparib through targeting RAD51 and suppressing homologous recombination in a panel of ovarian cancer cell lines." (PMID 26369335, 2015). "HR functionality was previously assessed in ascites of ovarian cancer patients and breast tumor biopsy samples by RAD51 ionizing radiation induced foci assay, and represent a potentially useful way of functional diagnostic testing to identify patients with HR deficiency." (PMID 26510816, 2015). "Importantly, depletion or inhibition of Rad51 dramatically increased the sensitivity of ovarian cancer cells to ATR and Chk1 inhibition, suggesting that HR deficiency and inhibition of ATR/Chk1 pathway can be synthetically lethal." (PMID 26295265, 2015). "In this study, we analysed the five RAD51 paralogs (RAD51B, RAD51C, RAD51D, XRCC2, XRCC3) in 142 unrelated patients with breast and/or ovarian cancer to estimate their contribution to breast and ovarian cancer predisposition." (PMID 24139550, 2013). "Importantly, both the risks for breast and ovarian cancer can also be modified by additional gene loci such as SNPs in RAD51 or BNC2 (Refs." (PMID 24025454, 2013). "This study reports RAD51 paralog analysis in breast and ovarian cancer cases." (PMID 24139550, 2013). "Several groups tested the comet assay and analysis of focal nuclear accumulations (foci) specific for γH2AX or RAD51 to monitor the dysfunction of DSB repair in family members with increased breast and ovarian cancer risk, and in primary ovarian carcinoma cell cultures." (PMID 23344037, 2013). "Interestingly, a recent study showed that KLF5 forms a transcriptional complex with EHF and ELF3 and binds to the promoter region of RAD51 to enhance its transcription, strengthening the homologous recombination repair pathway and consequently inducing chemoresistance in ovarian cancer cells." (PMID 39865088, 2025). "Therefore, we hypothesized that iron suppresses POLQ expression to enhance RAD51 mediated DNA repair, thus ultimately reducing the sensitivity of ovarian cancer to platinum." (PMID 38740757, 2024). "Also, we found that miR-506-3p overexpression could increase the sensitivity to Olaparib or cisplatin by targeting RAD51 in ovarian cancer cells." (PMID 38356722, 2024). "In addition, CDCA8 silencing sensitizes ovarian cancer cells to olaparib and cisplatin via induction of the G2/M phase arrest, acceleration of cell apoptosis, enhancement of DNA damage, and interference with RAD51 accumulation in vitro." (PMID 36855818, 2023). "HRD has been observed not only in ovarian cancer patients with germline or somatic BRCA1 or BRCA2 mutations but also in those with epigenetic silencing of BRCA1 or loss of function of other genes, such as ATM, ATR, BARD, BRIP, EMSY, PALB2, RAD51, and Fanconi Anemia Complementation Group genes." (PMID 36836518, 2023). "Therefore, RAD51 has predictive value in ovarian cancer and could be exploited as a predictive biomarker for survival and drug responsiveness." (PMID 33952262, 2021). "Accordingly, RAD51 might affect the prognosis of ovarian cancer." (PMID 33952262, 2021).
ovarian carcinoma (continued). "Furthermore, RAD51 expression affected immune infiltration in ovarian cancer." (PMID 33952262, 2021). "However, in spite of the importance of HR alteration in hereditary breast/ovarian cancer, mutations of the pivotal HR player RAD51 are surprisingly absent from the lists of genes predisposing individuals to breast or ovarian cancer." (PMID 34316706, 2021). "Notably, RAD51 affected PARP inhibitor responsiveness of ovarian cancer cell lines." (PMID 33952262, 2021). "Moreover, RAD51 affected DNA damage repair and drug responsiveness in ovarian cancer." (PMID 33952262, 2021). "Reduced RAD51 foci formation indicates HR deficiency and correlates with PARP inhibitor sensitivity, as shown in BRCA mutated breast tumor samples 2 h after 5 Gy of IR, ovarian cancer cell lines 8 h after 4 Gy of IR, and breast cancer patient-derived xenografts (PDXs)." (PMID 32029455, 2020). "The mRNA and protein expression levels in miR-509-3 overexpressing cells and NC cells were assessed by RT-qPCR and Western blot respectively and we found that miR-509-3 could significantly downregulate the mRNA and protein levels of HMGA2 and RAD51 in ovarian cancer cells." (PMID 32005272, 2020). "Moreover, like other cancer cell lines, transient silencing of PSIP1 in an ovarian cancer cell line significantly impaired DNA damage-induced RAD51 foci formation suggesting involvement of PSIP1 in the regulation of homologous recombination-mediated DNA repair." (PMID 26840454, 2016). "Currently, it has been found that RAD51 and PFKP, among others, undergo lactylation modification in ovarian cancer, and the lactylation modification of these proteins further enhances their resistance to platinum-based drugs in ovarian cancer." (PMID 41023769, 2025). "Our findings affirm the pro-cancer role of iron in ovarian cancer and reveal that iron advances platinum resistance by promoting DNA damage repair through FTH1/FTL/POLQ/RAD51 pathway." (PMID 38740757, 2024). "Many clinical trials, including trials evaluating drugs targeting ATR, ATM, WEE1, checkpoint kinase 1/2 (CHK1/2), BRCA1/2 and RAD51, have been designed to evaluate interference with DDR pathways to overcome platinum and PARPi resistance in ovarian cancer." (PMID 38539161, 2024). "The other case was a surgical ovarian cancer specimen with a germline RAD51C PV, showing HRD by GIS and HRP by RAD51 (32%)." (PMID 38648056, 2024). "Notably, while HRDlow sarcoma cells formed RAD51 nuclear foci upon olaparib- and trabectedin-induced DNA damage, neither formation of RAD51 nuclear foci nor increased RAD51 nuclear intensity were observed in HRDhigh sarcoma cells and BRCA1-mutated ovarian cancer cells." (PMID 39535612, 2024). "Specifically, highly expressed in ovarian cancer, KLF5 facilitated the process of ovarian cancer proliferation and metastasis and promoted PARP inhibitor resistance by remodeling the transcription of the key gene for homologous recombination, RAD51." (PMID 38773440, 2024). "Discordancy was observed in 1 ovarian cancer case with a germline RAD51D PV, which showed borderline results for both genomic instability and RAD51 foci (GIS of 42 and 13% RAD51)." (PMID 38648056, 2024). "Immunofluorescence staining revealed that inhibition of KLF5 reduced RAD51 foci and increased γ‐H2AX foci, suggesting that KLF5 plays a crucial role in regulating HRR in ovarian cancer cells." (PMID 37702443, 2023). "Other reported targets are HSP90 and VEGFR3 shown to attenuate RAD51, BRCA1, and BRCA2 expressions in ovarian cancer." (PMID 37370140, 2023). "In addition to the association between inherited ovarian cancer and RAD51, BRIP, and PALB2 pathogenic variants, MUTHY pathogenic variants confer an increased risk of ovarian cancer and may demonstrate resistance to platinum-based agents, much like tumours with mismatch repair deficiency." (PMID 36011309, 2022).